COL1A1 (collagen type I alpha 1 chain)
Diseases named in the same sentence as COL1A1 in open-access papers (continued):
Sharing a sentence is not in itself a finding about the gene and the disease.
liver fibrosis (continued). "In a separate cohort, we correlated hepatic gene expression levels of TREM2 with plasma ALT levels, as a measure of liver damage, hepatic gene expression levels of COL1A1, as a liver fibrosis marker, and with liver triglyceride (TG) levels, as a marker for hepatic steatosis." (PMID 36766683, 2023). "Collagen VI (COL6A1, COL6A2, and COL6A3) genes, but not COL1A1, have been associated with liver fibrosis." (PMID 38041174, 2023). "Similarly, S. japonicum miR-29b-3p prevents parasite-induced liver fibrosis by inhibiting COL1A1 and COL3A1." (PMID 37490505, 2023). "Finally, we looked at the early fibrosis markers Col1a1 and Hsp47, because cholestasis is thought to progress into liver fibrosis when left untreated." (PMID 35708773, 2022). "The higher quantities of COL1A1, Lama1, and Timp1 proteins were expressed in the model group, which were considerably subdued by PC administration, signifying that PC reduced CCl4-induced liver fibrosis." (PMID 35721129, 2022). "Additionally, the expression of α-SMA and COL1A1, markers of hepatic fibrosis, was measured by immunohistochemistry." (PMID 35123555, 2022). "Gene expression in liver fibrosis-related molecules such as Tgfb and Col1a1 was analyzed." (PMID 36296907, 2022). "Liver fibrosis monitored by the accumulation of α-Sma, collagen I, desmin, and Sirius red staining, as well as by measuring the mRNA levels of α-Sma, Col1a1, Mmp-3, and Tgfβ1, was significantly decreased by KY19334 treatment compared to treatment with selonsertib or ocaliva." (PMID 36114279, 2022). "Moreover, genes involved in hepatic fibrosis (that is, TGFβ1, COL1A1 and αSMA) were markedly increased in individuals with NASH compared with lean individuals or those with NAFLD and were also positively correlated with senescence markers." (PMID 35995996, 2022). "Obeticholic acid (OCA), an FXR agonist, prevents the activation of HSCs and reduces the fiber generates related to protein, such as Col1a1, α-smooth muscle actin, and tissue inhibitors of metalloproteinases-1, -2, significantly contributing to the improvement in liver fibrosis." (PMID 36313291, 2022). "Moreover, the mRNA expression of hepatic fibrosis markers, such as Col1a1 and Timp1, was significantly increased in CCl4-induced rats and repressed by Qijia Rougan decoction treatment." (PMID 35846987, 2022). "In addition, OCA ameliorates the degree of hepatic fibrosis and reduces the gene expression of Col1a1." (PMID 36588706, 2022). "In addition, the immunohistochemical results of α-SMA and COL1A1 further proved the pharmacological effects of GFL in the treatment of liver fibrosis." (PMID 36278176, 2022). "The mRNA levels of liver fibrosis markers (Acta2, Col1a1, Col3a1, and Timp1), cholangiocyte proliferation markers (Krt7 and Krt19), inflammation markers (Il6 and Il1b), and the progenitor cell marker (Sox9) were markedly decreased in miR-200c-BDL mice compared to con-BDL mice." (PMID 34880414, 2022). "Therefore, it was evident that GER inhibited the activation of HSCs in MCD diet-induced fibrosis, reduced the expression of COL1A1, and thereby improved liver fibrosis." (PMID 34675811, 2021). "In conclusion, this study indicates that rSjP40 inhibits the activity of COL1A1 promoter by increasing the expression of transcription factor Ets-1, down-regulating the expression of COL1A1, thereby inhibiting the activation of HSCs and inhibiting liver fibrosis." (PMID 34820381, 2021). "In addition, studies have found that Ets proto-oncogene 1 (Ets-1) suppresses the production of ECM by down-regulating matrix related genes such as COL1A1 induced by transforming growth factor β, and ultimately inhibits liver fibrosis." (PMID 34820381, 2021).
liver fibrosis (continued). "The molecules, including Scd1, Acta2, collagen type I alpha 1 chain (Col1a1), Timp1, Foxm1, Sult1e1, and plasminogen activator (Plat), are also involved in hepatotoxicity pathways, such as liver fibrosis, liver hyperplasia/hyperproliferation, liver proliferation, and liver necrosis/cell death." (PMID 34539442, 2021). "Moreover, the antifibrotic effect of NAOs was confirmed by immunoblotting and real-time PCR analysis of the major markers (PAI-1, α-SMA, and Col1A1) of liver fibrosis taken from three randomly selected mouse samples." (PMID 33670808, 2021). "Furthermore, expression of marker genes for hepatic fibrosis (Col1a1, Col1a2, Tgfb) and the immune cell marker Cd11c was higher in liver of AHKO mice fed HFD." (PMID 33692445, 2021). "Therefore, the expression level of COL1A1 can reflect the progression of liver fibrosis, inhibiting its expression will be one of the effective measures to reduce liver fibrosis." (PMID 34820381, 2021). "Similarly, the miR-21 inhibitor diminished the expression of α-SMA and Col1A1 in activated HSCs, by a mechanism with demonstrated therapeutic potential in liver fibrosis." (PMID 33574830, 2020). "The P10 hDPSC transplantation improved CCl4-induced liver fibrosis as indicated by the markedly suppressed area of fibrous tissue-deposition and the degree and expression of Col1a1 in the P10 hDPSC-transplanted group by Picrosirius Red staining, Ishak scoring, and qRT-PCR." (PMID 32213198, 2020). "Also, incubating LX2 cells with either GDF11 or TGF-β for 24 h led to significantly elevated mRNA levels of MMP2, αSMA/ACTA2, Col1A1 and Col5A1 — markers for stellate cell activation and liver fibrosis." (PMID 33126224, 2020). "Therefore, we chose to examine the expression levels for col1a1, ctgfa, and hpse as markers for liver fibrosis." (PMID 32570707, 2020). "The overexpression COL1A1 was reported to be highly correlated with liver fibrosis." (PMID 31902369, 2020). "Liver cMTO1 negatively correlated with liver Col1A1 expression, suggesting that cMTO1 may be involved in the progression of liver fibrosis." (PMID 32850833, 2020). "The in vivo pharmacodynamics study confirmed that compounds down-regulating the transcription of COL1A1 gene could effectively reverse liver fibrosis in vivo." (PMID 33121156, 2020). "Therefore, a luciferase screening cell model based on COL1A1 promoter was established earlier by the authors, and was successfully applied to the screening and evaluation of anti-hepatic fibrosis drug candidates." (PMID 31627430, 2019). "Knocking down MALAT1 alleviates liver fibrosis in mice through reducing Acta2 and Col1a1 levels." (PMID 30931332, 2019). "Importantly we observed that there was an increase in α-SMA+ cells as well as protein level of Col1a1 in Med23-deficient mouse livers, suggesting that Med23 ablation can also promote MCD diet–induced liver fibrosis." (PMID 31805036, 2019). "Additionally, hepatic Col1a1 and galectin‐3 levels were significantly reduced upon intake of Chios mastic gum, indicating a beneficial effect of treatment on liver fibrosis." (PMID 31599067, 2019). "The compound stood out in an anti-COL1A1 assay and effectively reversed liver fibrosis in vivo." (PMID 31627430, 2019). "Thus, the expression of many hepatic fibrosis markers such as Col1A1, FN1, MMP9 and TIMP1 was more abundant in GWI-BDL group than in naïve-BDL controls." (PMID 30177688, 2018). "Our results support the notion that siRNA or other epigenetic treatments for elevated Col1a1 levels may help in obesity-related liver fibrosis." (PMID 30526554, 2018). "Forced PTGIS expression in vivo through tail vein injection rAAV8-PTGIS can alleviate liver fibrosis, which was certified by the decreased COL1a1 and α-SMA protein and mRNA expression levels in primary HSCs isolated from fibrotic mice and the downregulated serum ALT/AST levels." (PMID 29892223, 2018). "In addition, we measured mRNA expression of α-SMA and Col1a1 to define the degree of hepatic fibrosis." (PMID 30071078, 2018).
liver fibrosis (continued). "Similarly, mRNA levels for Col1a1, a marker for hepatic fibrosis, was 4-fold higher in Pemt−/− mice treated with ezetimibe." (PMID 28159867, 2017). "The results showed that the collagen deposition and liver fibrosis caused by S. japonicum infection were markedly alleviated after DKK1 treatment, which was accompanied by a decrease in the expression of α-SMA/Acta2, desmin and Col1a1." (PMID 28331224, 2017). "Induction of COL1A1 and a-SMA is a hallmark of HSC activation and liver fibrosis." (PMID 27677421, 2016). "Additionally, considering the potential impact of using data from fibrotic samples on the results, analysis of HSCs using fibrosis markers Col1a1 and Col1a2 demonstrated a progressive worsening of liver fibrosis over time, indicating that the samples had not yet developed fibrosis." (PMID 40589742, 2025). "In addition, macrophage-specific Pparγ deficiency showed significantly increased expression of liver fibrosis-related genes, such as transforming growth factor-beta 1 (TGF-β1), actin alpha 2, collagen type I alpha 1 (COL1A1), and tissue inhibitor of metalloproteinase (TIMP)-1, in MASH liver." (PMID 39200340, 2024). "However, another report showed that activation of VDR did not improve the manifestation of preexisting pathology despite inhibiting the development of hepatic fibrosis by inhibiting collagen type I alpha 1 chain (COL1A1), tissue inhibitor of metalloproteinase (TIMP1) and α-SMA." (PMID 39478961, 2024). "As DNMT plays an important role in DNA methylation, DNMT inhibition may block the hypermethylation and downregulate related genes (such as PTGIS, PTEN, and Smad2/Smad3), inhibit the activation and proliferation of HSCs, inhibit the expression of α-SMA and COL1A1 in vitro, and delay liver fibrosis." (PMID 37056286, 2023). "The qPCR results showed that overexpression of miR-552-3p significantly reduced the mRNA levels of fibrotic genes (Col1a1, Col3a1, Timp-2) and inflammatory genes (Il-6, Ccl2, F4/80) in mice livers, which demonstrated that miR-552-3p could reduce liver fibrosis and inflammation in mice again." (PMID 37496991, 2023). "Expression of Col1a1, a major component of collagen, and of Tgfb1 an important promoter of fibrosis was also stronger following administration of the WD in WT mice compared with Pla2r1 KO mice, further supporting that Pla2r1 KO mice were protected from liver fibrosis." (PMID 37667516, 2023). "Notably, as a consequence of chronic liver damage, 5-month-old PTEN/SCAPΔL mice exhibited severe liver fibrosis, nearly cirrhosis, accompanied by a significant increase in type 1 collagen α1 (Col1a1) mRNA, whereas PTENΔL and SCAPΔL mice showed only very mild fibrosis at the same age." (PMID 35380992, 2022). "In addition to direct regulation of the COL1A1 gene, other proteins associated with collagen expressions, such as α-complex protein 2 (αCP2), transport and Golgi organization 1 (TANGO1), and HSP47, have been studied to treat liver fibrosis." (PMID 36435779, 2022). "In agreement with the increased liver fibrosis in TCDD-treated TiparpH532A mice, we observed higher gene expression levels of transforming growth factor β (Tgfb), zinc finger E-box binding homeobox 2 (Zeb2) and collagen type I alpha 1 chain (Col1a1), all of which are associated with fibrosis." (PMID 34129049, 2021). "Furthermore, the mRNA and protein levels of hepatic markers that could be used to determine the degree of liver fibrosis, such as Acta2, Col1a1 and Fn1 were markedly elevated by CCl4 but inhibited by SWT in different doses." (PMID 34736501, 2021).
liver fibrosis (continued). "Furthermore, hepatic mRNA levels of fibrogenic genes (Acta2, Col1a1, Col3a1, Col4a1, Tgfb1, Mmp13 and Vim) were significantly upregulated in miR-223KO mice compared with WT mice, suggesting that miR-223 deletion accelerated liver fibrosis." (PMID 33867837, 2021). "However, we cannot exclude the possibility that miR-125b may promote liver fibrosis by enhancing Col1a1 and Col1a2 expression." (PMID 30195793, 2018). "Therefore, inhibition of SREBF1 expression following overexpression of miR-185 might be a mechanism associated with the increases in COL1A1 and a-SMA levels during liver fibrosis." (PMID 27677421, 2016). "Among the genes, further analysis disclosed that the gene expression levels of TLR2, Col1a1, Col1a2, Col4a1, Col4a2, and Pdgfr-β were changed during the SCU anti-liver-fibrosis process, and qRT-PCR verified this result." (PMID 40243656, 2025). "In the pathophysiology of liver fibrosis, an imbalance in the synthesis and breakdown of the extracellular matrix (ECM) leads to the accumulation of the ECM, including type I collagen (COL1A1) and hyaluronic acid." (PMID 40649803, 2025). "In the present study, after DMDD treatment, hepatic TGF-β, Smad2, and Smad3 were significantly downregulated, and COL1A1, α-SMA, and TIMP1 were key genes in liver fibrosis." (PMID 40453659, 2025). "Accordingly, we found increased mRNA levels of liver fibrosis (Col1a1, Col3a1, α-Sma, Tgf-β1) and HCC markers (Afp and Gpc3) at 3 months and 6 months, suggesting the successfully constructed DEN/CCl4-induced liver fibrosis and primary HCC model." (PMID 40180937, 2025). "These cascades promoted HSC activation, myofibroblast differentiation, and ECM deposition (Col1a1, α-SMA), ultimately leading to liver fibrosis." (PMID 41042784, 2025). "Hepatic stellate cells (HSCs) are the key drivers of liver fibrosis, producing excess extracellular matrix (ECM) proteins like collagen-1 (COL1A1)." (PMID 40149485, 2025). "H&E staining of the liver indicated severe and diffuse necrosis in ChREBPα‐LKO mice, which also developed more advanced liver fibrosis, indicated by the elevated a‐SMA protein and Sirius staining and COL1A1 IHC." (PMID 40548862, 2025). "Although this study revealed the potential mechanisms of BPA-induced MASLD and provided an in-depth exploration of the crucial roles of the PI3K/AKT signaling pathway, COL1A1, COL1A2, and IGF1 in hepatic fibrosis, several limitations remain." (PMID 41306725, 2025). "A clear repression in hepatic fibrosis was observed in CeO2NP-treated groups as demonstrated by significant downregulation in TGF-β1 and p-Smad 2 and 3 proteins and COL1A1, MMP-2, and α-SMA expressions in hepatic tissues." (PMID 40679589, 2025). "On the basis of transcriptomics and network pharmacology findings, genes connected with liver fibrosis and the PI3K/AKT signaling pathway, such as Col1a1, Col1a2, Col4a1, Col4a2, TLR2, and Pdgfr-β, were chosen for qRT-PCR validation." (PMID 40243656, 2025). "Unexpectedly, SHS mice displayed reduced Col1a1 and Col1a2 expression, slightly lower PSR-staining intensity and significantly decreased liver collagen content on a liver fibrosis-inducing diet." (PMID 40475534, 2025). "Quantitative real-time polymerase chain reaction (qRT-PCR) elucidated the downregulation of key hepatic fibrosis markers (ACTA2, COL1A1, and SMAD2) upon exposure to crude KL extract." (PMID 39062514, 2024). "Correspondingly, the MCD diet elicited expression of liver genes related to liver fibrosis development, including α-SMA, Col1a1, and TGF-β, was also stimulated in hepatic Zbtb18LKO mice, along with an impaired expression of FXR and of its target genes." (PMID 38263084, 2024). "ICA was reported to reduce the expressions of Col1a1 and Acta2 in the livers from CCl4‐challenged mice and ameliorate thioacetamide (TAA)‐induced liver fibrosis in rats by inhibiting hepatic Col1a1 expression and collagen deposition." (PMID 39501714, 2024).
liver fibrosis (continued). "Consistently, we observed a significant reduction in liver fibrosis markers, including fibronectin (FN1) and collagen type I alpha 1 chain (COL1A1), as well as total hydroxyproline content in HKO mice." (PMID 39190492, 2024). "After Pip treatment, H&E staining, Oil Red O staining, hepatic triglyceride (TG) content and F4/80 expression were performed to analysis liver steatosis and inflammation; Masson’s staining, COL1A1 and α-SMA were detected liver fibrosis." (PMID 38547097, 2024). "In contrast, Col1A1, Timp1, and Tgfβ1 decreased, and Stat1 increased in both mRNA and protein levels following KIF18A overexpression in liver fibrosis models." (PMID 38372748, 2024). "We used COL1A1 as the primary endpoint, but vimentin, TGF-β1, and α-SMA were also monitored to closely track the state of the HSCs when modelling liver fibrosis." (PMID 38228622, 2024). "Sp1, an important transcription factor in liver fibrosis, is required for the regulation of fibrosis-related genes, such as CTGF, Col1A1, laminin and Smads32–36." (PMID 38243118, 2024). "Immunohistochemical staining revealed that the increased expression of liver fibrosis markers (α-SMA and COL1A1) in the fibrotic septa of the DDC group was decreased in the YCZFD treatment group." (PMID 38469403, 2024). "Collagen is a triple helical protein that is composed of 2 COL1A1 (α1) chains and 1 COL1A2 (α2) chain, and increased collagen synthesis by activated myofibroblasts is a major contributor to liver fibrosis." (PMID 39656528, 2024). "Then, by IHC analysis, we analyzed COL1A1 and COL3A1 levels, two key components of the extracellular matrix (ECM) altered during the progression of liver fibrosis." (PMID 38539791, 2024). "Conversely, NEAT1 overexpression stimulated HSC activation and increased αSMA and COL1A1 levels, indicating the involvement of NEAT1 in HSC activation and liver fibrosis." (PMID 39872125, 2024). "The same trend was observed in male Gpr183–/– compared to male WT with significantly lower levels of pro-inflammatory marker Il1β, liver fibrosis markers α-SMA, Col1a1, and Mcp1, and macrophage markers Adgre1 and Cd14." (PMID 39545055, 2024). "In the GSE55747 database, we found that EBI3, COL1A1 and COL3A1 mRNA expressions in mice of the liver fibrosis group were also higher than those of the normal group." (PMID 37480105, 2023). "Further analysis showed that the expression of FOXC2, α-SMA, Col1A1, FN1and CTGF, and hepatocellular damage were also reduced following with AAV6-shFOXC2 treatment in CCl4 or BDL-induced liver fibrosis model." (PMID 37705741, 2023). "This has been confirmed by detecting reduced protein and mRNA expression levels of COL1A1 and α-SMA and downregulation of serum ALT/AST levels in activated HSC-T6 cells and primary HSCs isolated from a liver fibrosis mouse model." (PMID 37056286, 2023). "The validation cohort showed GPC3 was negatively correlated with all liver fibrosis markers ACTA2, COL1A1, COL1A2, COL3A1 and ductular reaction markers KRT7 and KRT19, while SDC4 was positively correlated with ductular reaction index KRT19." (PMID 36816373, 2023). "Firstly, liver fibrosis (marker as ACTA2, COL1A1, COL1A2, COL3A1), reflected by proliferation of myofibroblasts and collagen deposition, is associated with decreased native liver survival mostly." (PMID 36816373, 2023). "Transcriptional levels of liver fibrosis markers (ACTA2, COL1A1, COL1A2, COL3A1) and ductular reaction markers (EPCAM, KRT7, KRT19) were significantly upregulated in BA." (PMID 36816373, 2023). "To quantify the amount of PDGFRβ-P2A-CreERT2-derived myofibroblasts, we used the triple transgenic PDGFRβ-P2A-CreERT2 x tdTomato x Col1a1-GFP mouse and induced liver fibrosis by CCl4." (PMID 37147343, 2023). "GR KO mice had 2.4-fold higher Pai-1 and 1.7-fold higher collagen 1a1 (Col1a1) mRNAs, suggesting a role of hepatocellular GR in the protection against HFHS-induced liver fibrosis." (PMID 35614477, 2022).